TRGV8 (T cell receptor gamma variable 8)
Description:
V region of the variable domain of T cell receptor (TR) gamma chain that participates in the antigen recognition. Gamma-delta TRs recognize a variety of self and foreign non-peptide antigens frequently expressed at the epithelial boundaries between the host and external environment, including endogenous lipids presented by MH-like protein CD1D and phosphoantigens presented by butyrophilin-like molecule BTN3A1. Upon antigen recognition induces rapid, innate-like immune responses involved in pathogen clearance and tissue repair. Binding of gamma-delta TR complex to antigen triggers phosphorylation of immunoreceptor tyrosine-based activation motifs (ITAMs) in the CD3 chains by the LCK and FYN kinases, allowing the recruitment, phosphorylation, and activation of ZAP70 that facilitates phosphorylation of the scaffolding proteins LCP2 and LAT. This lead to the formation of a supramolecular signalosome that recruits the phospholipase PLCG1, resulting in calcium mobilization and ERK activation, ultimately leading to T cell expansion and differentiation into effector cells. Gamma-delta TRs are produced through somatic rearrangement of a limited repertoire of variable (V), diversity (D), and joining (J) genes. The potential diversity of gamma-delta TRs is conferred by the unique ability to rearrange (D) genes in tandem and to utilize all three reading frames. The combinatorial diversity is considerably increased by the sequence exonuclease trimming and random nucleotide (N) region additions which occur during the V-(D)-J rearrangements.
Synonyms: TCRGV8; V1S8
Gene: T-cell receptor variable (V) gene on chromosome 7 (38,330,343 to 38,330,935, reverse strand). Ensembl gene ENSG00000211696.
Subcellular location: Cell membrane
Gene Ontology:
Cellular component: plasma membrane
Homologues: Orthologues: mouse Trgv7 (52% identical). Paralogues in human: TRGV4 (77% identical), TRGV2 (75% identical), TRGV5 (74% identical), TRGV3 (72% identical), TRGV1 (71% identical), TRGV11 (25% identical), TRGV9 (24% identical), TRGV10 (23% identical), TRGC1 (0% identical), TRGC2 (0% identical).
Diseases named in the same sentence as TRGV8 in open-access papers:
TRGV8 is named in the same sentence as 2 diseases in open-access papers, as found by Europe PMC text mining. Sharing a sentence is not in itself a finding about the gene and the disease.
TRGV8 shares sentences with these, for which no sentence is quoted: tumor (2 papers); prostate tumors (1).